IL2 (interleukin 2)
Diseases named in the same sentence as IL2 in open-access papers (continued):
Sharing a sentence is not in itself a finding about the gene and the disease.
tumor (continued). "When IHIC from bacterial-treated animals were cultured with tumor cells, the level of TNF enlarged, whereas the concentration of IL-2 decreased with respect to the unexposed culture from the same group." (PMID 26973649, 2016). "We found that adding IL-2 to a TLR7 agonist/CD40 agonist combination further enhanced CD8 T cell peak effector and memory response, and anti-tumor efficacy." (PMID 27660710, 2016). "Tumor-bearing mice were treated with different combinations of immunomodulatory antibodies (α-CTLA-4, α-PD-1, α-CD137) or interleukin-2 (IL-2) alone or in combination with SBRT." (PMID 27160390, 2016). "When we compared IL-2-activated CD52+ NK cells and CD52− NK cells, we found that CD52− NK cells exhibited 4-fold greater cytotoxicity against K562 tumor cells compared with CD52+ NK cells." (PMID 27560943, 2016). "On day 5, tumor engraftment was confirmed by BLI, and 107 CD123-CD28 or CD123-CD137 CAR+ T cells per mouse were infused together with IL-2 (60,000 units/mouse)." (PMID 27548616, 2016). "CART cells exposed to IL-2 or IL-15 lysed SKOV3 cells more efficiently than those exposed to IL-18 or NC, even at the lowest T cell to tumor ratio." (PMID 27409425, 2016). "Intracellular production of IL-2, TNF and IFNγ by tumor-specific T cells was examined after overnight stimulation with MCC peptide." (PMID 27121060, 2016). "Animal models showed that the HD IL-2 therapy activates and expands NK cells and CD8+ T cells mediating anti-tumor responses." (PMID 27153543, 2016). "Fourteen days after 4T1 tumor cells were injected into the mammary fat pad, mice were administered with activated TDLN B cells alone or TDLN B cells plus IL-2." (PMID 27528023, 2016). "Among the various cytokines, the combination of CART cells and IL-15 or IL-21 administration mediated the best anti-tumor response, followed by IL-2 and IL-7, whereas IL-18 and only CART cells treated mice had the heaviest tumor burden." (PMID 27409425, 2016). "While none of our immunotherapy approaches (including α-CTLA-4/α-PD-1, α-CD137/α-PD-1, IL-2) possessed any anti-tumor efficacy themselves, only α-CD137/α-PD-1 enhanced the anti-tumor effect of SBRT." (PMID 27160390, 2016). "IL-2 and IL-15-exposed CART cells secreted more proinflammatory cytokines and presented stronger tumor-lysis ability in vitro." (PMID 27409425, 2016). "To address this idea, we replaced infused tumor-specific CD8+ T cells, vaccination via fowlpox expressing hpg100 or high dose IL-2 with LPS in irradiated mice." (PMID 26885368, 2016). "More strikingly, in a two-tumor model, ECT was combined with an intratumoral administration of histocompatible IL2-secreting cells." (PMID 26993326, 2016). "In contrast, only 1 × 106 whole PBMCs (8-11% NK cells) were injected IP along with very low dose of IL-2 (1,000 U thrice weekly) to induce complete SKOV-3/GFP-Luc tumor remission in this study." (PMID 26802025, 2016). "The putative mediators of tumor inhibitory effect of supernatant from the irradiated cells seem to involve radiation-induced upregulation of VEGF, PDGF, GMCSF and IL-2 and downregulation of IL-6 and SCF." (PMID 27561007, 2016). "On the other hand, IL2-GMCSF can also act as a cytotoxic enhancer by pulling effector T cells and tumor cells close to promote specific immune killing." (PMID 26850448, 2016). "In order to confirm the establishment of anti-tumor immunity, we detected the changes in the proportion of the T cell subset in spleen by flow cytometry and the concentration of IFN-γ and IL-2 in serum by ELISA after Hep challenge." (PMID 26824185, 2016). "Stimulated splenocytes from vaccine-immunized mice with tumor cells induced an increased secretion of IFN-γ and IL-2." (PMID 27330408, 2016). "OT-I/iPS cells developed to CD8 CTL following adoptive transfer into recipient mice, produced IL-2 and interferon (IFN) after stimulation, and penetrated into tumor tissue after adoptive transfer." (PMID 27019752, 2016).
tumor (continued). "Cytokine profiling of the supernatants obtained from the irradiated tumor cells showed increased levels of VEGF, Rantes, PDGF, GMCSF and IL-2 and decreased levels of IL-6 and SCF." (PMID 27561007, 2016). "In a feedback loop, the hoisted B7-H3 and B7-H4 promoted T cells to secrete immunosuppressive cytokines IL-2, IL-6, IL-17, and TGF-β1, to maintain a tumor microenvironment." (PMID 27626488, 2016). "A possible reason for this difference is that we used NOD/SCID/IL2−/− mice for xenotransplantation, whereas the previous report used NOD/SCID mice, in which natural killer (NK) cells are active against tumor cells." (PMID 28123387, 2016). "Analysis of intracellular cytokine production was used to determine production of IFN, IL-2 and IFN- in tumor-infiltrating CD8+ T and natural killer (NK) cells and IL-10 production by T regulatory cells." (PMID 27178315, 2016). "The immune cells of this subset of patients can be activated to pronounced IL-2 production resulting Nap-specific expansion of CD4+ and CD8+ T cells which probably is a prerequisite for optimal Nap induced anti-tumour effects." (PMID 25669986, 2015). "The results of the present study revealed that IL-2 stimulated a positive immune response and reduced populations of Treg cells and MDSCs when combined with YM155 against the tumor immune response." (PMID 26023798, 2015). "In vitro NK cytotoxicity was assessed and NK cells and cytokines (IL-2, INF-γ, TGF-β) documented in tumours using immunohistochemical techniques." (PMID 26040463, 2015). "Adoptive cell transfer therapy is considered to provide large number of tumor reactive CD8T cells that secrete high levels of cytokines, IFNγ, TNFα, and IL-2." (PMID 26167500, 2015). "When used as vaccines in both prophylactic and pre-established tumor settings, the IL2-containing TEX were more effective than unmodified TEX or TEX mixed with IL2; CD4+, CD8+, and NK cells were all involved in the anti-tumor immunity." (PMID 26694473, 2015). "The Th1 response promotes host responses to tumours because IFN-γ and IL-2 can prime the CD8+ T cell response, thereby protecting the host by monitoring against tumour development." (PMID 25651850, 2015). "Our study revealed a higher level of salivary IL-2 in children with ALL as compared to the control group and a significant increase in the average cytokine value during the anti-tumour treatment." (PMID 25976216, 2015). "In contrast, ex vivo expanded Vδ1 T cells using Vδ1 mAb and IL-2 killed glioblastoma multiform (GBM) cell lines and primary tumor-derived GBM cells." (PMID 25686210, 2015). "Supernatants from IL-2 + anti-CD16mAb + sAJ2-treated NK cells in combination with both anti-TNF-α and anti-IFN-γ when added to OSCSCs restored tumor cell growth to the levels which were obtained with untreated OSCSCs." (PMID 26697005, 2015). "Flow cytometric analysis of tumor-infiltrating lymphocytes revealed that administration of IFN-γ and IL-2 downregulated the expression of CTLA-4 on CD3+ CD8+ TILs compared to control groups on day 14 post-transfer." (PMID 26107883, 2015). "Significant inhibition of the tumor growth was observed in the groups treated with both PAP-GMCSF alone and with the co-administration of PAP-GMCSF, -IL2, -IL4 and -IL7." (PMID 25632844, 2015). "NK cells treated with IL-2 + anti-CD16mAb + sAJ2 in combination with both anti-TNF-α and anti-IFN-γ when added to MP2 cells restored tumor cell growth to the levels obtained with untreated MP2 cells." (PMID 26697005, 2015). "These targeted IL-2 fusion proteins were shown to have tumor localization properties and to inhibit growth of CEA expressing tumor cells in transgenic mice." (PMID 25682197, 2015). "Following incubation of NK cells with Hsp70 protein or Hsp70 peptide plus IL-2, the density of CD94 was found to be significantly up-regulated concomitant with an increased cytolytic activity against mHsp70-positive tumor cells." (PMID 25926832, 2015).
tumor (continued). "TAMs can kill tumor cells following activation by IL-2, IFN-γ and IL-12, but they also produce IL-10, which inhibits the CTL-mediated antitumor response and therefore promotes tumor progression." (PMID 25663851, 2015). "The rationale for the combination of NHS-IL2 and radiotherapy was to modulate the immunologic microenvironment of the tumor by local irradiation and thereby enhance the IL-2–mediated effects of NHS-IL2." (PMID 25622640, 2015). "The simultaneous intraperitoneal administration of PAP-GMCSF, -IL2, -IL4 and -IL7 significantly prevented tumor induction and inhibited the tumor growth in the PAP-expressing tumors, yet not in the PSA-expressing tumors." (PMID 25632844, 2015). "Recently, many studies have shown evidence that IL-2 and IFN-γ played an important role in specific immunological reactions to tumor cell growth, and they promoted innate and adaptive immune responses." (PMID 26426041, 2015). "According to this study, TOB1 interacted with another tumor suppressor protein, SMAD4, and enhanced the binding of SMAD4 to the SMAD binding element (SBE) located on the promoter region of IL-2, thereby dampening IL-2 transcription." (PMID 26694352, 2015). "The co-administration of PAP-GMCSF, -IL2, -IL4 and -IL7 significantly prevented the tumor induction of PAP-RM9 cancer cells." (PMID 25632844, 2015). "Tumor volume, as analyzed by the IVIS instrument, was significantly smaller following YM155 and IL-2 combination therapy, as compared with treatment with IL-2 or YM155 alone (p = 0.000 and 0.026, respectively)." (PMID 26023798, 2015). "We evaluated the ability of T cells to function and produce IFN-γ, IL-2, IL-4, and IL-17 upon short-term stimulation with PMA and found very few differences in functional T cell capacity between NCF1*/* and NCF1*/+ tumor bearing mice." (PMID 26076008, 2015). "Upon directly recognizing cancer cells, TR-CD4 express an array of effector molecules, including IL-2, IFN-γ, TNF-α, perforin and granzyme, which play critical roles in inhibiting cancer cell growth and orchestrating anti-tumor immune responses." (PMID 26447332, 2015). "Lastly, they showed that the optimized treatment was able to fully regress the tumor for 35 days, whereas the controls (PBS and PBS + IL-2/IFNα) had little effect." (PMID 24949488, 2014). "The activation of CD4+ T cells contributes to the secretion of immune regulatory cytokines, including IL-2, IL-12, and IFN-γ, which in turn facilitate an elevation in the cytolytic CD8+ T cell responses, thereby inducing tumor cell death." (PMID 25412106, 2014). "Astragalus membranaceus polysaccharide improves immune response in the host individual by inducing IL-2, IL-12, and TNF-α secretion, as well as inhibits tumor progression in vivo." (PMID 24969238, 2014). "When Ad-hLF was administered to the tumor-bearing mice, the levels of serum IFN-γ and IL-2 were significantly increased and were close to the levels in the normal group (P<0.05)." (PMID 24520300, 2014). "Tumor tissue was analyzed for relative mRNA expression of a panel of different cytokines (IL1 β, IL2, IL6, IL18, TNF-α and IFN-γ)." (PMID 24676901, 2014). "chA21-28z CAR T cells recognized all of the HER2+ tumor lines and secreted IFN-γ and IL-2 at high levels." (PMID 24919843, 2014). "Mechanistic studies revealed that the major biologic effect of the successful doublets was restoration of IL-2 production and proliferation by CD8+ T cells within the tumor microenvironment." (PMID 24829760, 2014). "Because IL-2 can promote the long-term proliferation of T cells, TNF-α and IFN-γ can enhance immunoregulatory ability each other towards anti-tumor." (PMID 25068783, 2014). "Those which have been found to suppress tumor growth include IL-2, IL-12, IL-13 and IFN (gamma, beta and alpha) while IL-4, IL-6, IL-8 and IL-10 predominantly contribute to tumor growth." (PMID 24997057, 2014).
tumor (continued). "The work done by Low's group is detailed in explaining the tumor regression mechanism; however, further research is needed to understand if the treatment of folate-FITC along with IL-2 and IFNα can be effective." (PMID 24949488, 2014). "Tumor-secreted GM-CSF is involved in recruiting a population of MDSCs, which have been shown to inhibit IL-2 production from anti-CD3-activated intratumoral T cells and interfere with CD8+ T cell-mediated immunity at the tumor site." (PMID 24698959, 2014). "In the present study, the levels of IL-2 and IFN-γ were significantly increased, but the levels of IL-4 were reduced by hLF in tumor-bearing mice." (PMID 24520300, 2014). "They directly mediate the death of tumor cells, and also produce inhibiting factors such as IFN-γ, TNF-α and IL-2." (PMID 25594054, 2014). "Specifically, NK cells purified from human PBMCs cultured with ISO-66 showed increased killing of tumor targets (K562) and LAK cells generated with high concentrations of IL-2, when stimulated with ISO-66 efficiently lysed both K562 and Daudi targets." (PMID 25050663, 2014). "As IL-1α, IL-2, IL-6, TNF-α and IFN-γ are the major inflammatory cytokines secreted by immune cells activated by PHA, they are also located in the tumor microenvironment." (PMID 23761816, 2013). "Natural killer (NK) cells, which are another important effector cell type that has direct killing activity against tumor, have recently been shown to require CD4+ T cell help via IL-2." (PMID 24066030, 2013). "Our results indicate that 1,25(OH)2D3, the biologically active metabolite vitamin D3, calcipotriol and FTY720 augment IL-2-activated NK cell lysis of K562 and RAJI tumor cell lines as well as immature (i) and mature (m) DCs, with variable efficacies." (PMID 24169587, 2013). "Further, a recent paper demonstrated that the triple combination of IFN-γ, IL-2, and TNF-α represents a Th1 pattern of polycytokine secretion with greater antigen sensitivity and superior tumor recognition." (PMID 24195078, 2013). "These T cells effectively lysed a variety of CD20+ tumor cells at low E:T ratios and secreted abundant IFNγ, TNF-α, and IL-2 upon tumor recognition, highlighting their CD20 specificity and potent effector function." (PMID 24358223, 2013). "For example, interleukin-2 has been conjugated to an antibody specific for the FN1 isoform containing the extradomain-B, EDB, which is expressed during tissue remodelling in tumours." (PMID 24499539, 2013). "Ex vivo expansion of TIL with the IL-2-based systems greatly reduces CD27 and CD28 expression, resulting in reduced persistence and subsequent limited anti-tumor activity in vivo." (PMID 23402380, 2013). "This is particularly important in the light of a downregulation of NK cells and the immune cells containing interleukin 2, IL-17a (TH17) and IL-21 which suggests the influence of tumor cells on the innate immune system." (PMID 23877403, 2013). "PPD significantly increased WBC count, BMC count and the levels of IL-2 and IFN-γ in CTX-treated tumor-bearing mice." (PMID 23407364, 2013). "Given that IL-2 and inflammatory signals was shown to facilitate their production, one might speculate that the prevalence of such inflammatory cytokines/signals in the tumor surroundings may favor the recruitment or generation of these functionally mature effector Treg cells." (PMID 23874336, 2013). "The addition of Prostratin or the tumour-promoting phorbol ester, phorbol myristate acetate (PMA), after infection to the IL-2-depleted, FIV-infected cells stimulated virus production." (PMID 23201205, 2013). "We analyzed the production of IFN-γ, by intracellular staining, in three settings: in IL-2 activated NK cells, after stimulation with phytohemagglutinin (PHA) or after co-culture with the tumor target cells K562 at E/T ratio 1∶1." (PMID 24302998, 2013).
tumor (continued). "CAR-expressing T cells produced abundant quantities of IL-2, INF-γ, and TNF-α, demonstrating activation of both cytolytic and cytokine effector mechanisms after tumor recognition." (PMID 24358223, 2013). "All three drugs examined augment in vitro IL-2-activated NK cell lysis of K562 and RAJI tumor cell lines, as well as immature and mature DCs, with variable efficacies." (PMID 24169587, 2013). "In this assay, we evaluated the production of multiple cytokines (IFNα, TNFγ, and IL-2) and upregulation of LAMP-1 (CD107a) by tumor- (Melan-A/MART-1) specific T-cells." (PMID 24195078, 2013). "Our data confirm that IL-2 and IL-15 improve CD8+ T cell activation and induction of prophylactic tumor immunity, also when incorporated in a coronavirus-based vaccine that delivers the cytokines directly to DCs in vivo." (PMID 24312302, 2013). "The majority of tumor-derived Tim-3+ CD4 T cells exhibited an impaired capacity to produce IFN-γ and IL-2, but expressed higher levels of CD25, Foxp3, CTLA-4 and GITR than their Tim-3− CD4 T cell counterparts." (PMID 23526963, 2013). "The production of the IL-2, IL-10, IFN-γ and TGF-β cytokines was observed in the B16F10 cells and also detected in the tumoral microenvironment during tumor growth (7, 14 and 21 days)." (PMID 24179494, 2013). "IL-2 and INF-γ levels were significantly decreased in CTX-treated tumor-bearing mice as compared with those of the control group (P<0.01)." (PMID 23407364, 2013). "PPD significantly increased the peripheral white blood cell count, bone marrow cell count, interleukin-2 and interferon-γ in CTX-treated tumor-bearing mice." (PMID 23407364, 2013). "IL-2 modulates or promotes major histocompatibility complex (MHC) antigen expression, driving the tumour towards regression." (PMID 23927575, 2013). "Since anti-OX40 and IL-2 has been shown to modulate Treg function, we sought to investigate the effects of dual anti-OX40/IL-2 therapy on Tregs in tumor-bearing hosts." (PMID 22496812, 2012). "Indeed, studies reporting complete regression of tumor in mice were performed by intratumoral injection of T cells expressing chimeric receptors and/or addition of intravenous IL-2, or vaccination with autologous LCLs, which may have allowed for improved T-cell survival and in vivo expansion." (PMID 22272203, 2012). "Tumor-exosomes can inhibit lymphocyte, predominantly CD4+ T cell proliferation in response to IL2, which is accompanied by impaired CD25 up-regulation and stronger suppressive activity of regulatory T cells (Treg), possibly due to exosome-associated TGFβ1." (PMID 23190502, 2012). "ASMq treated animals had reduced tumour volume compared to model and increased concentrations of TNF-α, IL-1β and IL-2 compared to untreated and to cyclophosphamide-treated animals." (PMID 22978453, 2012). "More importantly, IL-15 and IL-2 treatment overcame ligand-induced NKG2D downregulation, enabling NK cells to exhibit substantially enhanced cytotoxicity against tumor cells." (PMID 22629344, 2012). "In this study, to overcome the tumor-induced immunotolerance, a simple and safe strategy with IFN-α and/or IL-2 was used to selectively and efficiently downregulate Treg and upregulate NK cells in malignant patients." (PMID 22722448, 2012). "However, other studies have suggested that IL-2 therapy may stimulate tumor cell growth." (PMID 20953429, 2011). "These "young" TILs are tumor-reactive, positively skewed in CD8+ lymphocyte composition, CD28 and CD27 expression, and contain fewer FOXP3+ T cells compared to parallel IL-2 cultures." (PMID 21827675, 2011). "More importantly, immunotherapy with interferon alpha (IFN-α) or interleukin 2 (IL-2) can produce even complete and durable response in advanced RCC and tumour vaccines have shown to have some response, too." (PMID 21929816, 2011).